LRP1 (LDL receptor related protein 1)
Diseases named in the same sentence as LRP1 in open-access papers (continued):
Sharing a sentence is not in itself a finding about the gene and the disease.
tumor (239 papers, 2009 to 2026). "Collectively, these results suggest that LRP1 deficiency drives tumor‐promoting activities in HCC cells by accelerating ubiquitin‐dependent degradation of OGA." (PMID 39405202, 2024). "To elucidate the mechanisms underlying the induction of PD-L1 expression by PAI-1, we prepared tumor cell lines deficient in uPAR (uPAR-KO) or LRP-1 (LRP1-KO) using the CRISPR/Cas9 system." (PMID 38779680, 2024). "Immunohistochemistry confirmed the expression of LRP1 in Cancer-Associated Fibroblasts (CAFs) and macrophages in the tumor microenvironment of BLCA." (PMID 37153545, 2023). "In this case, low cell surface expression of LRP1 is linked to high expression of urokinase-type plasminogen activator (uPA) which is known to induce tumor cell invasion." (PMID 37020553, 2023). "Deconvolution algorithms and single-cell analysis were used to understand the tumor-infiltrated cells and biological pathways associated with LRP1 expression." (PMID 37153545, 2023). "The KM survival analysis showed that elevated LRP1 expression was linked to tumor progression and negatively affected patients’ progression-free survival (PFS) (p=0.003)." (PMID 37153545, 2023). "Initial studies on LRP1’s possible role in cancer were mainly on tumor cell lines, and suggested that reduction of Lrp1 expression or even a complete loss of the gene is associated with cancer development." (PMID 37020553, 2023). "This manuscript provides insight into the close association of LRP1 with stromal remodeling and immune infiltration in the tumor microenvironment of BLCA through systematic bioinformatics analysis, literature search, and real-world cohort validation." (PMID 37153545, 2023). "As LRP-1 showed significant differential expression among different tumor subgroups and was associated with proliferative activity, the effect of this molecule was studied in the U87MG and LN229 cell lines." (PMID 36267880, 2022). "Inhibition of LRP-1 was associated with decreased NOTCH signaling which is one of the important pathways to regulate the proliferative activity of the tumor cells." (PMID 36267880, 2022). "The implication of LRP1 (also known as CD91, encoded by Lrp1) in tumor immunosurveillance has been well documented, providing a highly efficient conduit for the cross-presentation of tumor antigens to T cells." (PMID 36430209, 2022). "Bu’s group showed that miR-205 down-regulates the expression of LRP-1 and causes decreased migration of several tumour cell lines via MMP2 and MMP99,10." (PMID 35835845, 2022). "To confirm that the loss of LRP1 inhibited tumor growth due to the inability of tumors to repress Tsp-1, we crossed the LysM-Cre-LRP1−/− with Tsp1−/− mice to generate double-knockout (DKO) mice that lacked Tsp-1 globally and LRP1 in myeloid cells." (PMID 36575174, 2022). "The surface-exposed Calr facilitates the engulfment of tumor-associated antigens by binding to LRP1/CD91 on DCs to initiate an immune response." (PMID 31924786, 2020). "In summary, low LRP1 expression evaluated by immunohistochemistry and by qRT-PCR in two independent cohorts is strongly associated with right tumor location, MSI-H, BRAF mutation and CIMP-H." (PMID 29507659, 2018). "Then, LRP1 mutation was strongly associated with female gender (p < 0.0001), right tumor location (p = 0.04), MSI-H (p < 0.0001) and CIMP-H status (p = 0.0006)." (PMID 29507659, 2018). "On multivariate analyses, low LRP1 IHC score in tumor cells was associated with right location (p = 0.0004), MSI-H (p = 0.01) and BRAFV600E mutation (p = 0.009)." (PMID 29507659, 2018). "In our cohort, low LRP1 IHC score in tumor cells was associated with poor OS particularly in metastatic (stage IV) patients." (PMID 29507659, 2018). "As in our cohort, LRP1 mRNA expression levels among the TCGA cohort were significantly lower in cases with right tumor location (p = 0.0003), MSI-H (p < 0.0001), BRAF mutation (p = 0.0015) CIMP-H (p < 0.0001) and low CDX2 expression (p < 0.0001)." (PMID 29507659, 2018).
tumor (continued). "Low LRP1 immunohistochemical expression in adenocarcinomas was associated with higher age, right-sided tumor, loss of CDX2 expression, Annexin A10 expression, CIMP-H, MSI-H and BRAFV600E mutation." (PMID 29507659, 2018). "In patients treated with bevacizumab (n = 37), low LRP1 IHC score in tumor cells was associated with shorter OS." (PMID 29507659, 2018). "Low density lipoprotein (LDL) receptor-related protein 1 (LRP1) is a ubiquitously expressed multi-ligand endocytosis receptor implicated in a wide range of signalling, among others in tumour biology." (PMID 28662213, 2017). "Similar to LRP1, the truncated splice variant smLRP1 is ubiquitously expressed in healthy human tissues, but altered in tumours pointing to a potential role of smLRP1 in cancer." (PMID 28662213, 2017). "Intriguingly, Staudt and colleagues demonstrated that in a subcutaneous PanO2 pancreatic cancer isograft model, macrophage LRP-1 deficiency induces macrophage infiltration into tumor, expression of proinflammatory chemokines, and tumor angiogenesis." (PMID 25514242, 2014). "LRP1 encodes a membrane-bound receptor that has been implicated in tumor cell invasion, migration, proliferation, and apoptosis." (PMID 25300797, 2014). "In general, LRP1 modulates MMP9 expression and low level of LRP1 in HCC cells is associated with tumor aggressiveness in HCC." (PMID 22427881, 2012). "Consistent with our results, previous studies have reported a decreased phosphorylation of ERK-1/2 in LRP-1-deficient non-tumor cells." (PMID 20644732, 2010). "Intriguingly, among these 11 significantly associated genes, Lrp1, Abca1, Map4k4, Vegfa, and Nf1 regulate cell efferocytosis, micropinocytosis, and endocytic activities in DCs, macrophages, and tumor cells." (PMID 37508356, 2023). "Furthermore, the ssGSEA algorithm revealed that LRP1 was positively correlated with the activities of tumor-associated pathways." (PMID 37153545, 2023). "In the current study, we have focused our investigation specifically on how cell surface LRP-1 takes over to support tumour cell migration under the loss of environmental support, reminiscent to lack of support from the blood circulation during tumour invasion and metastasis." (PMID 35835845, 2022). "Thus, LRP1 IHC score on tumor cells was associated with peculiar clinicopathological and molecular characteristics." (PMID 29507659, 2018). "The loss of LRP1 expression in tumor cells is partly explained by mutations in LRP1 gene." (PMID 29507659, 2018). "Hence, dysregulation of LRP1 expression is associated with pathogenic states such as atherosclerosis, Alzheimer disease, and tumours." (PMID 28662213, 2017). "Together, the roles of monocyte- and macrophage-associated LRP1 in the initiation and progression of tumor suggest that targeted regulation of the inflammatory environment may prevent the occurrence of tumors." (PMID 26738504, 2016). "Moreover, tumor-associated, LRP1-deficient macrophages were characterized by the release of vascular endothelial growth factor (VEGF) into the tumor microenvironment." (PMID 26738504, 2016). "Accumulation of extracellular proteolytic activities associated to the tumor microenvironment could explain at least in part why cell-surface LRP1 is generally found decreased in advanced tumors." (PMID 26617523, 2015). "Notably, stable expression of the β∆‐chain significantly reduced the tumor burden in nude mice bearing LRP1‐deficient cells, decreasing the tumor volume and weight to a level lower than that in mice bearing control cells, although the difference was not significant." (PMID 39405202, 2024). "Furthermore, surface-exposed calreticulin (CALR), which interacts with LDL receptor-related protein 1 (LRP1), serves as a de novo uptake signal and facilitates DC-mediated phagocytosis of tumor cells, hence resulting into the transfer of tumor-associated antigens into antigen-presenting cells." (PMID 37907944, 2023).
tumor (continued). "Interestingly, increased PDAC aggressiveness was associated with the tumor cell-mediated uptake of CAF-derived ANXA6+ EVs carrying the ANXA6/LRP1/TSP1 complex, whereas the depletion of ANXA6 in CAFs impaired the complex formation and subsequently the occurrence of metastasis." (PMID 36614326, 2023). "It has been demonstrating that the interaction between MDK and its receptor Lrp1 is significantly positively correlated with the infiltration of M2 macrophages in the tumor microenvironment, while negatively correlated with the infiltration of M1 macrophages." (PMID 41276912, 2026). "LRP1 also drives tumorigenesis and tumor progression by activating AKT/mTOR signaling and inhibiting JNK and NF-κB pathways." (PMID 40625660, 2025). "Serum proteomics reveals that irradiated tumour-secreted PAI-1 triggers the fate transition of distant tumour pericyte cells into SFRP2-high CAFs via the LRP1/p65 axis." (PMID 41009413, 2025). "Lactoferrin-modified liposomes (LF-lipo) achieve active targeting via LRP-1, which is highly expressed across diverse tumor types, enabling highly selective tumor delivery and suitability for systemic administration to treat metastatic lesions." (PMID 41311720, 2025). "In summary, our findings demonstrate that DS elicits anti-tumor immunity by targeting LRP1 and engaging DCs, T cells, and macrophages." (PMID 40625660, 2025). "Surface-exposed CRT binds DC-expressed CD91 (LRP1), enhancing DC phagocytosis of dying tumor cells and cross-presentation of TAAs to CD8+ T cells, activating tumor-specific CTLs." (PMID 41314288, 2025). "LRP1, expressed by tumor-infiltrating macrophages, promoted the differentiation of immunosuppressive macrophages." (PMID 40777026, 2025). "Consistently, the amount of LRP1 captured by DS–biotin was dramatically reduced in LRP1 knockout (LRP1KO) tumor cells generated using CRISPR-Cas9." (PMID 40625660, 2025). "We also validated one of our predicted novel personalized driver genes on tumor cell proliferation by vitro cell-based assays, the promoting effect of the high expression of Low-density lipoprotein receptor-related protein 1 (LRP1) on tumor cell proliferation." (PMID 38683860, 2024). "In various models and clinical trials, blocking LRP1 has been shown to enhance phagocytosis, leading to a reduction in tumour burden both in vitro and in vivo." (PMID 39063239, 2024). "Through our analysis, we have revealed LRP1’s significant involvement in tumour progression and various cellular processes and signalling pathways." (PMID 39063239, 2024). "LRP1 also affects the intensity of the tumor-specific CD8+ T cell immune response by influencing the expression levels of the antigen cross-presentation-related gene MHC-I." (PMID 38835772, 2024). "Spatial enrichment analyses focused on the SERPINA1_LRP1 pair revealed a strong concentration within the tumor area." (PMID 39081317, 2024). "We investigated the relationship between LRP1 expression and tumour purity across various cancers by analysing the ESTIMATE score." (PMID 39063239, 2024). "An increase in MDK results in an interaction with its receptor LRP1, which is expressed by tumour-infiltrating macrophages and promotes immunosuppressive macrophage polarization." (PMID 38896142, 2024). "Research has found that the recognition and uptake of apoptotic tumor cells by DCs depend on the binding of calreticulin on the apoptotic tumor cell surface to its receptor LRP1, which can activate tumor-specific CD8+ T cells." (PMID 38835772, 2024). "According to the authors, the malignant properties of the tumour can be inhibited by acting on the low-density lipoprotein receptor-related protein 1 (LRP1), which is a receptor for A2M." (PMID 38612805, 2024). "PAI-1 participates in the regulation of tumor invasion and angiogenesis through interactions with binding partners such as LRP1 and uPAR." (PMID 38779680, 2024).
tumor (continued). "Immunohistochemical analysis showed that the pJNK, MMP2, and Ki-67 protein levels were significantly increased in tumor tissues of LRP1–SNRNP25-overexpressing cell-injected nude mice." (PMID 38678020, 2024). "Mechanistically, the PAI-1 secreted by tumor cells induced the surface expression and secretion of PD-L1 by tumor cells via the LRP1/uPAR/JAK/STAT axis." (PMID 38779680, 2024). "LRP1, as an active endocytosis receptor for the protease inhibitor α2MR, influences crucial cellular processes in tumour progression." (PMID 39063239, 2024). "To address this, we evaluated LRP1 expression in human HCC tumor tissues and investigated the role of LRP1 in the tumorigenicity of HCC cells in vivo and in vitro using gain‐ and loss‐of‐function methods." (PMID 39405202, 2024). "Influences dormant tumor cell polarity for lamellipodia formation for cell motility via an eHSP90α–LRP1 interaction.Confers an immune modulatory and protective effect on tumor cells by regulating the expression of immune suppressive factors." (PMID 38994941, 2024). "LRP1 expression and its function in cancer are context-dependent, varying across different types of tumours and stages of disease, making LRP1 both a prospective target for therapeutic intervention and a possible biomarker for cancer prognosis." (PMID 39063239, 2024). "Increased PDAC aggressiveness was dependent on the tumor cell-mediated uptake of CAF-derived ANXA6-positive EVs carrying the ANXA6/LRP1/THBS1 complex." (PMID 38892190, 2024). "LRP1’s implication in OC pathogenesis supports its suitability for targeted therapies to disrupt tumour-promoting pathways and bolster anti-tumour immune responses." (PMID 39063239, 2024). "The authors observed that the interaction between the eHSP90α-specific component and its client protein LRP1 affects tumor cell motility by altering the polarity of the cell through the development of lamellipodia." (PMID 38994941, 2024). "MDK secreted by tumor epithelial cells binds to its receptor LRP1 on macrophages, promoting the infiltration of immunosuppressive macrophages." (PMID 38951896, 2024). "The tumor volume, weight, and ratio of liver weight to body weight in nude mice with orthotopic liver implantation of LRP1 knockdown MHCC‐97H cells were significantly increased compared to those in control mice at the end of the experiment." (PMID 39405202, 2024). "Relative to normal tissues, LRP1 exhibited consistently lower expression in tumour samples of LUSC but was significantly expressed in tumour samples of KIPAN, HNSC, KIRC, OC, and PAAD." (PMID 39063239, 2024). "The pivotal functions of LRP1 in tumour immunity and metabolism extend its therapeutic potential beyond OC." (PMID 39063239, 2024). "To gain a better understanding of how LRP1 impacts extracellular matrix and tumor microenvironment-related pathways, we investigated the levels of LRP1-related immune and stromal cell infiltration." (PMID 37153545, 2023). "The capacity of LRP1 to induce endocytosis and transmit cell signals plays many functions in carcinogenesis and tumor growth." (PMID 37124542, 2023). "Our results suggested a significant adverse effect of high LRP1 expression in the tumor microenvironment on the prognosis of BLCA patients." (PMID 37153545, 2023). "To reinforce our findings from the TCGA database, we conducted a thorough analysis of the connection between LRP1 expression levels and pathways related to the tumor microenvironment by merging two BLCA sequencing databases from GEO (GSE13507 and GSE32894)." (PMID 37153545, 2023). "LRP1 is a cell surface receptor involved in invasion and neovascularization, processes that drive tumor progression and metastasis." (PMID 36973740, 2023). "Along with the results of previous literature, we systematically summarized the potential functions played by LRP1 in the tumor microenvironment of BLCA." (PMID 37153545, 2023).
tumor (continued). "We have been investigating the role of leukemia specific antigen Proteinase 3 (P3) in modulating anti-tumor immune response and identified LRP1 on T cells as the direct mediator of T cell proliferation." (PMID 37020553, 2023). "Enrichment analysis demonstrated that LRP1 was involved in extracellular matrix remodeling and tumor metabolic processes." (PMID 37153545, 2023). "Previous studies suggest that MPs recognize tumor-associated antigens (TAA) through Fcy or lectin-like receptors, as well as LDL receptor-related protein 1 (LRP1)." (PMID 37345089, 2023). "Our present findings have expanded the knowledge of LRP1/ligand interactions in regulating tumor progression." (PMID 37310025, 2023). "In tumor cells, LRP1, as the endocytic receptor of MMP2 and MMP9, can make malignant cells in an adherent state by activating ERK and inhibiting the JNK signaling pathway, which is conducive to invasion 49,50,51." (PMID 36605486, 2023). "The surface-exposed CRT/ERp57 complex binds low-density lipoprotein receptor-related protein 1 (LRP1, better known as CD91) on the DC membrane, promoting phagocytosis, tumor antigen cross-presentation and activation of antitumor CTLs." (PMID 36949244, 2023). "For example, in TAMs, gene expression of FPR3, PLAUR, and LRP1, the receptor genes interacting with tumor cells, was correlated with ligand genes interacting with CD8+ T cells including C5AR1." (PMID 38002057, 2023). "In contrast, LRP1 is downregulated in areas of tumor invasion, thus enabling upregulation CXCR3-A upregulation on cell membranes, causing tumor strand migration and promoting invasion." (PMID 38104126, 2023). "Given the close relationship between LRP1 and tumor immune modulators, we wanted to know if the expression level of LRP1 affects the responsiveness to immunotherapy in BLCA patients." (PMID 37153545, 2023). "That is, blocking the binding of PAI-1 to LRP1 and uPA at the same time through combined therapy can inhibit tumor growth and metastasis and signal pathway activation from multiple aspects, thereby improving the therapeutic effect." (PMID 36605486, 2023). "Immature dendritic cells (DCs) and macrophages express the transmembrane receptor CD91 (also known as LRP1) on their surface that interacts with CRT on tumor cells." (PMID 36831197, 2023). "This work established a direct link between intracellular signaling pathways modulated by LRP-1 and dynamics of matrix attachment of migrating tumor cells." (PMID 36052226, 2022). "Strikingly, the knockdown of PRSS2 in tumor cells and knockout of LRP1 in myeloid cells potently inhibited tumor growth in mouse models of breast and pancreatic cancer, with tumors having higher levels of Tsp-1 in the TME." (PMID 36575174, 2022). "Deve’s group reported that LRP-1 regulates cancer-signalling events to support tumour vascular morphology and functionality during angiogenesis." (PMID 35835845, 2022). "Considering the deep consequences of LRP-1-dependent regulation of calpain activity on the invasive potential and adhesion/deadhesion processes of tumor cells, we then analyzed the distribution and the morphology of cytoskeleton constituents." (PMID 36052226, 2022). "In that context, the maintenance of baseline calpain activity by LRP-1 is therefore permissive to efficient tumor cell motility." (PMID 36052226, 2022). "The migratory ability and invasiveness of the tumor cells were also significantly reduced compared to control after LRP-1 knock-down in both the cell lines." (PMID 36267880, 2022). "Only combined inhibitions of the EGFR signalling and the eHsp90α autocrine signalling led to the full blockade of the tumour cell migration as the LRP-1 depletion did." (PMID 35835845, 2022). "The previous finding suggested that, besides the “secreted Hsp90α > LRP-1 receptor” autocrine pathway, LRP-1 regulates another independent signalling pathway to achieve a full control of the self-supported tumour cell motility." (PMID 35835845, 2022).